ARL15 (ARF like GTPase 15)
Synonyms: ARFRP2; FLJ20051
Tractability: PROTAC: ubiquitination databases record sites on it; its protein half-life has been measured.
Gene: Protein-coding gene on chromosome 5 (53,883,942 to 54,310,582, reverse strand). Ensembl gene ENSG00000185305.
Subcellular location (Human Protein Atlas): Microtubules; Primary cilium; Basal body; Cytokinetic bridge; Mitotic spindle
Gene Ontology:
Molecular function: protein binding; GTP binding; GTPase activity
Cellular component: extracellular exosome
Genetic constraint (gnomAD): Loss-of-function variants: 14 observed, 16.78 expected, observed/expected ratio (o/e) 0.83, 90% interval 0.55 to 1.3. The upper end of that interval is the gene's LOEUF score, 1.3, which puts it in group 5 of 6, group 1 being the genes least tolerant of losing a copy. Missense variants: 182 observed, 198.88 expected, observed/expected ratio (o/e) 0.92, 90% interval 0.81 to 1.03. Synonymous variants: 80 observed, 71.08 expected, observed/expected ratio (o/e) 1.13, 90% interval 0.94 to 1.36.
Homologues: Orthologues: chimpanzee ARL15 (100% identical), macaque ARL15 (99% identical), guinea pig ARL15 (98% identical), mouse Arl15 (97% identical), rat Arl15 (92% identical), dog ARL15 (91% identical), tropical clawed frog arl15 (81% identical), zebrafish arl15b (78% identical), rabbit ARL15 (75% identical), pig ARL15 (71% identical), zebrafish arl15a (69% identical). Paralogues in human: ARF1 (31% identical), ARF3 (31% identical), ARF5 (30% identical), ARF6 (29% identical), ARL13B (29% identical), TRIM23 (29% identical), ARF4 (28% identical), ARL4D (28% identical), ARL3 (28% identical), ARL1 (27% identical), ARL2 (26% identical), ARL8B (26% identical), and 18 more.
Diseases named in the same sentence as ARL15 in open-access papers:
ARL15 is named in the same sentence as 35 diseases in open-access papers, as found by Europe PMC text mining. Sharing a sentence is not in itself a finding about the gene and the disease. The quoted sentences say what the papers report.
Insulin resistance (7 papers, 2009 to 2020). Increased resistance towards insulin, that is, diminished effectiveness of insulin in reducing blood glucose levels. "We suggest that a possible role for heterozygous ARL15 loss-of-function variants in pathological adipose remodelling and insulin resistance-related traits merits further study." (PMID 29242557, 2017). "Variants within ARL15 are associated with decreased adiponectin levels and nominally associated with risk of T2D, coronary heart disease and insulin resistance as measured by HOMA-IR." (PMID 27312935, 2016). "Although the relationship between ARL15 and diabetes has been reported, the mechanism of how ARL15 is associated with insulin resistance remains unknown." (PMID 31623319, 2019). "These associations implicate that ARL15 variants may play a role in insulin resistance leading to T2D susceptibility independently of BMI." (PMID 26363598, 2015). "Therefore, ARL15 may either play a causative role in insulin resistance or an adaptive response to enhance insulin action." (PMID 31623319, 2019). "Therefore, effects of ARL15 variants may be mediated via insulin resistance and/or adiponectin trafficking." (PMID 26363598, 2015). "Many loci associated with adiponectin levels are shared with other insulin resistance traits and risk of type 2 diabetes, including loci near IRS1, LYPAL1, ARL15/FST, VEGFA, CMIP, and PEPD." (PMID 32915782, 2020). "Proteins involved in inflammation (FIBA, TRFE, and KNG1) and insulin resistance (ARL15 and RET4) were abundantly excreted in the urine samples of metabolically unhealthy obese individuals compared to the metabolically healthy obese individuals." (PMID 31623319, 2019). "Thus, ARL15 is a good candidate to be involved in cellular insulin resistance and/or adiponectin trafficking and secretion." (PMID 20011104, 2009). "Thus, while the human genetic studies we describe do not prove that ARL15 haploinsufficiency gives rise to or predisposes to lipodystrophic insulin resistance, we suggest that this possibility warrants further study." (PMID 29242557, 2017).
type 2 diabetes (7 papers, 2015 to 2025). "The small GTPase ARF family member ARL15 gene locus is associated in population studies with increased risk of type 2 diabetes, lower adiponectin and higher fasting insulin levels." (PMID 34779483, 2021). "Finally, it has been described that ARL15 overexpression inversely influences circulating adiponectin levels, which has been linked to a higher risk and susceptibility to type 2 diabetes, coronary heart disease, and rheumatoid arthritis." (PMID 39858027, 2025). "ARL15 played a role in type 2 diabetes susceptibility and fasting insulin regulation." (PMID 31623319, 2019). "We confirmed associations with type 2 diabetes for five of the seven SNPs (TMEM154-rs6813195, FAF1-rs17106184, POU5F1/TCF19-rs3130501, ARL15-rs702634 and ABCB9/MPHOSPH9-rs4275659)." (PMID 25799151, 2015). "A trans-ethnic meta-analysis of type 2 diabetes genome-wide association studies has identified seven novel susceptibility variants in or near TMEM154, SSR1/RREB1, FAF1, POU5F1/TCF19, LPP, ARL15 and ABCB9/MPHOSPH9." (PMID 25799151, 2015). "We examined the association of six SNP loci, rs6813195 near TMEM154, rs9505118 in SSR1, rs17106184 in FAF1, rs3130501 in POU5F1, rs702634 in ARL15, and rs4275659 near MPHOSPH9, identified by transethnic GWAS meta-analysis with susceptibility to type 2 diabetes in a Japanese population." (PMID 27115357, 2016). "We performed a replication study in a Japanese population to evaluate the association between type 2 diabetes and six susceptibility loci (TMEM154, SSR1, FAF1, POU5F1, ARL15, and MPHOSPH9) originally identified by a transethnic meta-analysis of genome-wide association studies (GWAS) in 2014." (PMID 27115357, 2016).
diabetes (5 papers, 2016 to 2021). "In addition to the direct relationship between ARL15 and diabetes, an association between ARL15 and diabetes-related atherosclerosis has been reported." (PMID 31623319, 2019). "In addition, higher levels of ARL15 in urine may help in the prediction of the increased risk of diabetes in MUHO individuals." (PMID 31623319, 2019). "Indeed, ARL15 has been associated with a wide range of metabolic parameters and diseases in GWAS, including adiponectin, HDL, diabetes mellitus and body shape." (PMID 34089346, 2021). "Similarly, the diabetes gene Arl15 was described to improve insulin-mediated AKT phosphorylation in myotubes." (PMID 34445304, 2021). "In addition, ARL15 was identified recently as a new candidate gene related to diabetes." (PMID 31623319, 2019).
coronary artery disease (4 papers, 2012 to 2025). "A recent meta-analysis of three GWAS for adiponectin levels identified variants in a novel candidate gene, ARL15, that were associated with adiponectin levels, coronary heart disease (CHD), T2D and other metabolic traits." (PMID 22479202, 2012). "Several intronic single nucleotide polymorphisms (SNPs) at the ARL15 locus have been associated with components of the metabolic syndrome and its sequelae including plasma adiponectin, insulin, HDL cholesterol, and triglyceride concentrations, and coronary artery disease." (PMID 29242557, 2017).
kidney cancer (3 papers, 2021 to 2025). Primary or metastatic malignant neoplasm involving the kidney. "Elsewhere ARL15 has been found associated as a pro-survival protein, reducing reactive oxygen species (ROS), with both metabolic conditions and kidney cancers." (PMID 34432858, 2021). "Overexpression of ARL15 in various kidney cancer cell lines increased CNNM3’s molecular weight, indicating enhanced glycosylation in the presence of ARL15." (PMID 40003994, 2025). "Kidney cancer cells were stably transduced to either overexpress or produce a CRISPR knockout of ARL15." (PMID 34089346, 2021). "Mg2+ uptake experiments with a stable isotope demonstrate that there is a significant increase of 25Mg2+ uptake upon knockdown of ARL15 in multiple kidney cancer cell lines." (PMID 34089346, 2021).
lipodystrophy (3 papers, 2017 to 2021). A congenital or acquired disorder characterized by abnormal loss or redistribution of the adipose tissue in the body. "Previously, loss of ARL15 was shown to reduce insulin secretion in a human β-cell line and loss-of-function mutations are found in some lipodystrophy patients." (PMID 34779483, 2021). "Further, loss-of-function mutations in the ARL15 gene have also been identified in lipodystrophy patients." (PMID 34779483, 2021).
Obesity (3 papers, 2017 to 2021). Accumulation of substantial excess body fat. "Common genetic variants at the ARL15 locus are associated with plasma adiponectin, insulin and HDL cholesterol concentrations, obesity, and coronary atherosclerosis." (PMID 29242557, 2017).
renal carcinoma (2 papers, 2021 to 2025). A carcinoma arising from the epithelium of the renal parenchyma or the renal pelvis. "Overexpression of ARL15 in renal carcinoma cells decreased cellular Mg2+ uptake, whereas KO of the protein increased it." (PMID 34928937, 2021).
rheumatoid arthritis (2 papers, 2022 to 2025). A chronic, systemic autoimmune disorder characterized by inflammation in the synovial membranes and articular surfaces. "Genetic studies have implicated the ARL15 gene locus in rheumatoid arthritis and multiple metabolic diseases." (PMID 35834310, 2022).
breast carcinoma (1 paper, 2022). "To explore the role of Arl15 in cancer metastasis, we assessed two key metastatic traits in vitro, cellular migration and invasion, using a highly metastatic breast cancer cell line – MDA-MB-231." (PMID 35834310, 2022). "A similar result was obtained when Arl15 was depleted in the MDA-MB-231 cell line, representing highly metastatic breast cancer cells." (PMID 35834310, 2022).
cutaneous melanoma (1 paper, 2025). A primary melanoma arising from atypical melanocytes in the skin. "Recently, a bioinformatic study has provided the first evidence that the low expression of ARL15 is associated with a favorable prognosis in cutaneous melanoma." (PMID 39858027, 2025).
dilated cardiomyopathy (1 paper, 2024). Cardiomyopathy which is characterized by dilation and contractile dysfunction of the left and right ventricles. "Different from the prediction result of LASSO, in the cardiac fibroblasts, we recognized the up-regulation of ARL15 for dilated cardiomyopathy, which has already been reported previously." (PMID 39202774, 2024). "ARL15 (ADP Ribosylation Factor Like GTPase 15, 604699) has been widely shown to be associated with dilated cardiomyopathy by multiple machine learning models with reliable literature support." (PMID 39202774, 2024). "The specific role of ARL15 (ADP Ribosylation Factor Like GTPase 15, 604699) in dilated cardiomyopathy prediction, XIST (X Inactive Specific Transcript) for hypertrophic cardiomyopathy, and hypoplastic left heart syndrome has been validated." (PMID 39202774, 2024).
cancer (6 papers, 2008 to 2025). A tumor composed of atypical neoplastic, often pleomorphic cells that invade other tissues. "ARL15 was first linked to cancer as an independent prognostic factor in cutaneous melanoma (CM), a particularly deadly skin cancer." (PMID 40003994, 2025). "(e, f) Arl15 missense mutations identified from cancer patients compromise Arl15-Smad4 interaction and TGFβ signaling." (PMID 35834310, 2022). "Using cancer genomic databases, we explored mutations in cancer patients that can disrupt Arl15-Smad4 interaction." (PMID 35834310, 2022). "(j, k) Cancer missense mutations in the MH2 domain of Smad4 can compromise Arl15-Smad4 interaction." (PMID 35834310, 2022). "However, the finding of mutations compromising the Arl15-Smad4 interaction in the cancer genomic database suggests that Al15 might be a tumor suppressor." (PMID 35834310, 2022). "Conversely, high ARL15 expression in colon cancer was linked to the upregulation of metabolic and lipogenic proteins, including FASN, AKT, SREBP-1 (p125), and AMPK, promoting migration and invasion in cancer cell models." (PMID 40003994, 2025). "Notably, the TGFβ signaling pathway can be tumor-suppressive or pro-metastatic, depending on the context, adding complexity to ARL15’s role in cancer." (PMID 40003994, 2025). "Our observation that Arl15 is required for the efficient invasion and migration of malignant cancer cells suggests that it might be a pro-metastatic factor." (PMID 35834310, 2022). "In addition, a literature search showed that FAM9C was identified to have several roles in cancer development such as promoting the tumor growth in the liver, while ARL15 was found to regulate adiponectin levels, which were dysregulated in cancer." (PMID 28981542, 2017). "We identify several novel candidate cancer genes including Rreb1, Mmp13 and Arfrp2 (Arl15)." (PMID 18485879, 2008). "Therefore, we hypothesize that, like Smad4, Arl15 might play a similar dual-role in cancer progression." (PMID 35834310, 2022). "Therefore, our observation correlates the activity of Arl15 with a gene transcription profile characteristic of the TGFβ-induced cytostasis and EMT in cancer cells." (PMID 35834310, 2022).
tumor (5 papers, 2008 to 2023). "A novel candidate tumor suppressor emerging from this comparison is Arfrp2 (Arl15)." (PMID 18485879, 2008). "Since CM is a highly immunogenic type of tumor, after discovering that ARL1, ARL11, and ARL15 expression may have a significant impact on CM patients’ prognosis, we investigated whether the immune microenvironment could be involved in the mechanisms associated with ARL prognostic value." (PMID 34502169, 2021).
metabolic disease (1 paper, 2022). A congenital disorder (due to inherited enzyme abnormality) or acquired (due to failure of a metabolically important organ) disorder resulting from an abnormal metabolic process. "Consistent with the broad role of the TGFβ signaling pathway in physiology and pathology, our findings raise the likelihood of ARL15 as the causative gene and suggest the contribution of the TGFβ family signaling pathway to the pathology of these metabolic diseases." (PMID 35834310, 2022). "Therefore, our findings warrant a further investigation of the role of Arl15 in metabolic diseases." (PMID 35834310, 2022).
ARL15 also shares sentences with these, for which no sentence is quoted: alcohol dependence (1 paper); atherosclerosis (1); bladder cancer (1); calculus (1); cervical cancer (1); clear cell renal cell carcinoma (1); congenital adrenal hyperplasia (1); coronary atherosclerosis (1); hepatocellular carcinoma (1); Hypertension (1); hypertrophic cardiomyopathy (1); hypoplastic left heart syndrome (1); leiomyosarcoma (1); lung carcinoma (1); metabolic syndrome (1); papillary renal cell carcinoma (1); partial lipodystrophy (1); primary lipodystrophy (1); prostate carcinoma (1); yolk sac tumour (1).